IL1RN (interleukin 1 receptor antagonist)
Diseases named in the same sentence as IL1RN in open-access papers (continued):
Sharing a sentence is not in itself a finding about the gene and the disease.
aortitis (2 papers, 2019 to 2023). Inflammation of the aorta. "We aimed to investigate the preclinical model of aortitis in BALB/c IL1rn−/− mice using [18F]fluorodeoxyglucose ([18F]FDG) positron emission tomography–magnetic resonance (PET-MR), gamma counting and immunostaining." (PMID 38019303, 2023). "This first study, including [18F]FDG PET-MR in the IL1rn−/− mouse model of aortitis at 9 weeks old, demonstrates the fit of this IL1rn−/− mouse model with GCA for the key pro-inflammatory and pathogenic cytokines." (PMID 38019303, 2023). "In the present study, we demonstrated that IL-25 is crucial for development of IL-1–, TNF– and IL-17–mediated aortitis in Il1rn−/− mice." (PMID 31745167, 2019). "The development of aortitis in Il1rn−/− mice is dependent mainly on IL-1 and TNF, and at least in part on IL-17A22,23." (PMID 31745167, 2019). "Here, we demonstrate that IL-25 plays a facilitative role in the development of IL-1–, TNF– and IL-17A–mediated aortitis in Il1rn−/− mice." (PMID 31745167, 2019). "Regarding this, using bone marrow cell transfer analysis, we showed that IL-25 derived from non-hematopoietic cells rather than immune cells was crucial for development of IL-1–, TNF– and IL-17–mediated aortitis in Il1rn−/− mice." (PMID 31745167, 2019). "DC-derived IL-1β and macrophage-derived TNF are thought to subsequently activate Th17 cells to induce IL-17, contributing to development of aortitis in Il1rn−/− mice." (PMID 31745167, 2019). "CD3+ T cells, CD11c+ DCs, Gr1+ neutrophils, Mac2+ macrophages and tryptase+ mast cells had infiltrated the lesions of aortitis in Il1rn−/− mice." (PMID 31745167, 2019). "On the other hand, in the local lesions of aortitis in Il1rn−/− mice, we identified CD11c+ DCs, Mac2+ macrophages, γδ T cells and B cells as IL-25 receptor (IL-17RB)–expressing cells." (PMID 31745167, 2019). "In our model, IL-25 deficiency resulted in reduced expression of Il17a and Tnfa mRNA in the aortae of Il1rn−/− mice, suggesting that IL-25 somehow enhanced the development of IL-1–, TNF– and IL-17–mediated aortitis in Il1rn−/− mice." (PMID 31745167, 2019). "However, Il25−/−Il1rn−/− mice showed attenuated development of aortitis compared with Il1rn−/− mice, indicating that IL-25 contributed to exacerbation—not suppression—of IL-1–, TNF– and IL-17–mediated aortitis in Il1rn−/− mice." (PMID 31745167, 2019). "It was reported that the development of aortitis was diminished in Il1r1−/−Il1rn−/− mice and Tnfa−/−Il1rn−/− mice, whereas it was normal in Il6−/−Il1rn−/− mice, indicating that IL-1α and/or IL-1β, and TNF are crucial for development of aortitis in Il1rn−/− mice." (PMID 31745167, 2019). "Indeed, the incidence of aortitis in Il25−/−Il1rn−/− mice was significantly lower than in Il1rn−/− mice." (PMID 31745167, 2019). "On the other hand, our results suggest that IL-25 may enhance production of IL-6, IL-17A and TNF, but not IL-23, thereby contributing to development of IL-1–, TNF– and IL-17A–dependent aortitis in Il1rn−/− mice." (PMID 31745167, 2019). "Th17 cell-derived IL-17A contributes to development of aortitis in Il1rn−/− mice." (PMID 31745167, 2019). "We found that expression of II25 mRNA was increased in the aortae of Il1rn−/− mice, suggesting that IL-25 may suppress development of IL-1–, TNF– and IL-17A–dependent aortitis in Il1rn−/− mice by inhibiting type 3-mediated immune responses." (PMID 31745167, 2019). "IL-25 enhanced IL-1β and TNF production by IL-25 receptor–expressing dendritic cells and macrophages, respectively, at inflammatory sites of aortae of Il1rn−/− mice, contributing to exacerbation of development of IL-1–, TNF– and IL-17A–dependent aortitis in those mice." (PMID 31745167, 2019). "The development of aortitis was attenuated, but not completely abrogated, in Il25−/−Il1rn−/− mice compared with Il1rn−/− mice." (PMID 31745167, 2019).
aortitis (continued). "Il1rn−/− mice transferred with Il25−/−Il1rn−/− BM cells developed aortitis similarly to Il1rn−/− mice transferred with Il1rn−/− BM cells, indicating that IL-25 produced by BM cell–derived immune cells was not essential for development of aortitis in Il1rn−/− mice." (PMID 31745167, 2019).
bronchitis (2 papers, 2013 to 2023). An acute or chronic inflammatory process affecting the bronchi. "The association of MUC5AC with bronchitis is only significant in individuals who lack the IL1RN*2 (risk) allele and only in individuals homozygous for the ERBB1 common rs2227983(R) allele—that is non-carriers of the rarer K allele." (PMID 23551418, 2013). "A novel association between bronchitis and an ERBB1/EGFR SNP rs2227983 was also identified and possible gene–gene interactions between MUC5AC and ERBB1 and IL1RN are described." (PMID 23551418, 2013). "A novel association between bronchitis and a non-synonymous functional ERBB1 SNP, rs2227983 (aka epidermal growth factor receptor:R497K, R521K) is also reported and evidence presented of interaction between MUC5AC and ERBB1 and between MUC5AC and IL1RN with respect to bronchitis." (PMID 23551418, 2013). "Significant interactions with respect to bronchitis were identified between MUC5AC rs1132440 and ERBB1 rs2227983 (P = 0.019), IL1RN VNTR (P = 0.009) and TNFA rs1800629 (P = 0.046)." (PMID 23551418, 2013).
cervical carcinoma (2 papers, 2020 to 2021). A carcinoma arising from either the exocervical squamous epithelium or the endocervical glandular epithelium. "The interleukin-1 receptor antagonist (IL-1RN) polymorphism is associated with cervical cancer." (PMID 34150619, 2021).
chronic gastritis (2 papers, 2015 to 2018). Inflammation of the stomach that is chronic in nature. "In the context of such subjects, the effects of polymorphism in two cytokine genes, the pro-inflammatory cytokine IL-1B and anti-inflammatory cytokine IL-1RN, in relation to the development of peptic ulcer and chronic gastritis were analyzed." (PMID 30320011, 2018).
depression (2 papers, 2025 to 2026). "Additionally, air pollution can activate inflammatory response pathways (e.g., IL1RN, galectin-3, CLEC4D, CASP8), disrupting neurotransmitter balance and exacerbating neuronal inflammation, thereby increasing the incidence of depression." (PMID 40611827, 2025).
dermatomyositis (2 papers, 2014 to 2020). Dermatomyositis (DM) is a type of idiopathic inflammatory myopathy characterized by evocative skin lesions and symmetrical proximal muscle weakness. "There is only one previous report of IL1RN VNTR polymorphism associated with dermatomyositis (DM) in a Bulgarian population." (PMID 33330522, 2020).
E. coli infection (2 papers, 2017 to 2025). "However, only two of them (IL1RN, CD20037) had also been induced by the E. coli infection." (PMID 28684793, 2017).
endometrial cancer (2 papers, 2019 to 2020). Primary or metastatic malignant neoplasm involving the endometrium (mucous membrane that lines the endometrial cavity). "We first targeted dCas9-VP16(10x) and dCas9-p300(core) to the IL1RN promoter, a gene which can be highly activated by CRISPRa, and observed a similar level of activation for IL1RN with both dCas9 fusion constructs in Ishikawa cells, an endometrial cancer cell line." (PMID 31570515, 2019).
endometritis (2 papers, 2016 to 2022). An acute or chronic, usually bacterial infectious process affecting the endometrium. "The top three upstream regulators predicted to be inhibited in the endometrium of pregnant cows after uterine infection include 1) MAPK1 (kinase); 2) NKX2-3 (transcription regulator); and 3) IL1RN (cytokine)." (PMID 35358206, 2022).
experimental autoimmune encephalomyelitis (2 papers, 2011 to 2015). An autoimmune demyelinating disease of the central nervous system that is produced experimentally in animals by the injection of homogenized brain or spinal cord in Freund's adjuvant. "Further, IL1RN gene therapy improves the course of experimental autoimmune encephalomyelitis, the animal model of MS." (PMID 22216338, 2011).
gastritis (2 papers, 2008 to 2015). Inflammation of the stomach. "The biopsy specimen having gastritis without H. pylori infection (No 8) revealed an IL1RN-VNTR 2/2-genotype." (PMID 18842150, 2008). "Capillary electrophoresis revealed an IL1RN-VNTR 1/1-genotype in six (No 9, 21, 22, 25, 27, 28), a 1/2-genotype in four (No 6, 12, 14, and 18), and a 2/2-genotype in one (No 23) of the H. pylori-infected gastritis biopsies." (PMID 18842150, 2008).
Hepatic fibrosis (2 papers, 2013 to 2017). The presence of excessive fibrous connective tissue in the liver. "When compared to the WDB group, the WDO group displayed increased hepatic expression of genes linked to inflammation (Opn, Il1rn, Gdf15), hepatic fibrosis (collagen staining, Col1A1, Thbs2, Lox) reflecting disease progression." (PMID 28422962, 2017). "The model of advanced hepatic fibrosis (P < 0.006) included only IL1RN (P < 0.006) as a sole component explaining 34% of the variance in fibrosis (R2 = 0.34)." (PMID 23661906, 2013). "Expression levels of soluble interleukin 1 receptor antagonist (IL1RN) were correlated with the presence of NASH and hepatic fibrosis." (PMID 23661906, 2013).
infertile (2 papers, 2012 to 2021). "Distribution of VNTR of IL1RN genotypes and alleles among infertile patients and fertile controls." (PMID 23251650, 2012).
liver disease (2 papers, 2011 to 2025). "Conversely, IL1RN showed up-regulation in T1DM-associated liver disease but decreased expression after NAC treatment." (PMID 40001479, 2025). "Biomarkers previously associated with liver diseases and identified in our samples were among others: ANGPTL3, IGFBP2, SDC4, IL1RN." (PMID 21978410, 2011).
lymph node metastasis (2 papers, 2020 to 2021). "The methylation level of IL1RN was negatively correlated with its expression level and was also correlated with the disease stage, lymph node metastasis, and pathological type." (PMID 33238942, 2020). "Patients with an advanced clinical stage, advanced T stage and lymph node metastasis tended to have decreased IL1RN methylation levels." (PMID 33238942, 2020). "Furthermore, high expression of IL1RN was significantly correlated with clinical stage, lymph node metastasis and pathological type." (PMID 33238942, 2020). "In our study, IL1RN was significantly positively correlated with lymph node metastasis and tumor stage, so we speculated that IL1RN might also promote tumor aggressiveness and poor prognosis through immune-related mechanisms in PTC." (PMID 33238942, 2020). "The IL-1RN rs419598 wild-type genotype was significantly related to stage III-IV disease, the PIGR rs291102 wild-type genotype was significantly related to normal levels of CYFRA, and the BCL2 rs2279115 wild-type genotype was significantly related to lymph node metastasis." (PMID 34150619, 2021). "The IL-1RN rs419598 wild-type genotype was significantly related to stage III-IV disease, the PIGR rs291102 wild-type genotype was significantly related to normal levels of cytokeratin fragment 19 (CYFRA), and the BCL2 rs2279115 wild-type genotype was significantly related to lymph node metastasis." (PMID 34150619, 2021).
mastitis (2 papers, 2019 to 2022). Inflammation of breast tissue during lactation or postpartum due to an obstructed duct or infection. "Among these, seven genes (CXCR1, HCK, IL1RN, MMP9, S100A9, GRO1, and SOCS3) were identified as the hub genes and these can be explored as potential candidate genes for mastitis susceptibility and resistance." (PMID 35723402, 2022). "The most important overexpressed genes in cows with mastitis were GRO1, CXCR1, SOCS3, S100A9, MMP9, HCK, and IL1RN, which were hub genes (highly connected genes) involved in mastitis in this study." (PMID 35723402, 2022). "Among these, seven genes—CXCR1, HCK, IL1RN, MMP9, S100A9, GRO1, and SOCS3—were identified as the hub genes (highly connected genes) for mastitis susceptibility and resistance, and were subjected to protein-protein interaction (PPI) network and gene regulatory network construction." (PMID 35723402, 2022). "In the case of the cytokine–cytokine-receptor interaction pathway, other genes, such as CD40, IL1RN, CXCR1, TNFRSF6B, and CCL19, were found to be involved in mastitis defense or immune response, as all these genes were upregulated in the mastitic cows based on their FC values." (PMID 35723402, 2022).
Migraine (2 papers, 2025). "Consistent with Il1b emerging as a shared hub, a prior study using a familial hemiplegic migraine model reports IL1RN upregulation after cortical spreading depression." (PMID 41465107, 2025).
myocardial infarction (2 papers, 2020 to 2022). Gross necrosis of the myocardium, as a result of interruption of the blood supply to the area, as in coronary thrombosis. "A study reported that tH3 of the gene (IL1RN) encoding IL-1Ra, a natural inhibitor of the pro-inflammatory cytokine IL-1, was associated with an increased risk of myocardial infarction." (PMID 35231061, 2022).
periodontal disease (2 papers, 2019 to 2023). "Four of them, IL1B (p = 0.023), IL1RN (p = 0.048), BGLAP (p = 0.0372) and PTK2 (p = 0.0075) were down-regulated in the periodontal disease and implant rejection group, and only one was overexpressed: FOXO1A (p = 0.0552)." (PMID 37175429, 2023).
rectal cancer (2 papers, 2022 to 2024). A primary or metastatic malignant neoplasm that affects the rectum. "In the case of rectal cancer (READ), significantly higher IL-1RN gene expression was observed, with a median of 12.1 in READ versus 7.9 in the normal rectum (log FC 0.62, p = 1.5 × 10−2)." (PMID 39766795, 2024). "The results of UALCAN analysis showed that the expression levels of both IL1RN and PRRX1 were significantly higher in colon and rectal cancer samples than in healthy samples." (PMID 36483329, 2022).
tendinopathy (2 papers, 2024 to 2025). "These in vitro data helped to explain the therapeutic efficacy of SM 102 LNPs- Il1rn mRNA in the mouse model of tendinopathy." (PMID 40873435, 2025).
urothelial carcinoma of the urinary bladder (2 papers, 2014 to 2020). "For IL1RN, its low expression is an early driver of carcinogenesis of urothelial carcinoma of the urinary bladder." (PMID 32977823, 2020).
vitiligo (2 papers, 2016 to 2018). Generalized well circumscribed patches of leukoderma that are generally distributed over symmetric body locations and is due to autoimmune destruction of melanocytes. "IL1RN intron 2 VNTR (rs1794068) has been found to be associated with autoimmune disorders including vitiligo." (PMID 27454254, 2016). "Genomic DNA was extracted from whole blood of 226 vitiligo patients and controls for IL1RN VNTR genotyping." (PMID 27454254, 2016). "In addition, IL-1 inhibitory IL1RN (p < 0.05) showed a slight increase in vitiligo non-lesional skin." (PMID 30515176, 2018). "We have explored the role of Interleukin (IL)-1 in vitiligo by monitoring the expression of IL1A, IL1B, IL1Receptor1 (R1) and IL1 Receptor Antagonist (RN) in skin samples, effect of IL1-α on melanocyte viability, IL1R1 membrane expression and genotyping of IL1RN VNTR in Gujarat population." (PMID 27454254, 2016).
acute esophagitis (1 paper, 2022). "The interleukin 1 (IL1) family pathway with its downstream effectors (IL1A, IL1R1, IL1RN, IL1B) are esophagus-specific genes and were shown in previous studies to be linked, among others, with the development and progression of acute esophagitis and BE." (PMID 35328735, 2022).
acute lung injury (1 paper, 2014). A condition of lung damage that is characterized by bilateral pulmonary infiltrates (pulmonary edema) rich in neutrophils, and in the absence of clinical heart failure. "Interleukin-1 receptor antagonist (IL-1RA) produced by MSCs serves as a key factor for inhibiting macrophage-mediated inflammation in acute lung injury (ALI)." (PMID 25124290, 2014).
acute lymphoblastic leukemia (1 paper, 2024). Leukemia with an acute onset, characterized by the presence of lymphoblasts in the bone marrow and the peripheral blood. "Genotyping of interleukin 1 receptor antagonist (IL1RN) polymorphisms has shown that the IL-1RN*2 genotype is associated with an increased risk of septic shock in children with acute lymphoblastic leukemia." (PMID 38716051, 2024).
allergic rhinitis (1 paper, 2022). Inflammation of the nasal mucous membranes caused by an IgE-mediated response to external allergens. "It was stated that differences in genotype distribution “was mainly due to an increased number of IL1A allele G homozygotes and IL1RN allele 2 homozygotes in allergic rhinitis”." (PMID 36518750, 2022).
alveolitis (1 paper, 2022). "IL1RN gene polymorphisms may be associated with susceptibility to fibrosing alveolitis, a disease characterized by interstitial lung fibrosis." (PMID 35935869, 2022).
Alzheimer disease (1 paper, 2025). A progressive, neurodegenerative disease characterized by loss of function and death of nerve cells in several areas of the brain leading to loss of cognitive function such as memory and language. "In summary, IL1RN and IL-6 inhibitors demonstrate substantial potential in treating a variety of immune-related diseases, particularly osteoporosis and Alzheimer's disease." (PMID 40153574, 2025).
aspiration pneumonia (1 paper, 2022). "One of the unexpected findings was that APOE was the SNP associated with aspiration pneumonia, which contradicts previous findings that reported that the major allele of rs4252961 in IL1RN was associated with infection risk." (PMID 36005151, 2022).
carotid atherosclerosis (1 paper, 2013). A thickening and loss of elasticity of the walls of carotid arteries that occur with formation of atherosclerotic plaques. "In addition, variations in the genes that regulate the IL-1 response have been associated with CHD; allele 2 of IL-1RN VNTR*2 (IL-1RN*2) was significantly associated with single vessel disease (SVD) and carotid atherosclerosis." (PMID 23691333, 2013).
cervical squamous cell carcinoma (1 paper, 2011). A squamous cell carcinoma arising from the cervical epithelium. "Evidence also suggests that IL1RN activity may play an important role in the development of cervical squamous cell carcinoma." (PMID 21457566, 2011).
chronic obstructive pulmonary disease (1 paper, 2019). A chronic and progressive lung disorder characterized by the loss of elasticity of the bronchial tree and the air sacs, destruction of the air sacs wall, thickening of the bronchial wall, and mucous accumulation in the bronchial tree. "Similar patterns, including trends towards dose-dependent increases in IL-6 and also IL-1RN and FGF-7 were observed in mRNA levels from hMSCs exposed to two separate CF and one chronic obstructive pulmonary disease (COPD) BALF samples." (PMID 31553626, 2019).
Cirrhosis (1 paper, 2024). A chronic disorder of the liver in which liver tissue becomes scarred and is partially replaced by regenerative nodules and fibrotic tissue resulting in loss of liver function. "In contrast, the inflammatory cytokine interferon gamma-induced protein 10 (IP10) (IVW-OR = 0.707, 95% CI: 0.516–0.969; p = 0.031) and interleukin-1 receptor antagonist protein (IL-1RA) (IVW-OR = 0.725, 95% CI: 0.548–0.959; p = 0.024) were associated with a reduced risk of cirrhosis." (PMID 39457577, 2024).
cryopyrin-associated periodic syndrome (1 paper, 2025). Cryopyrin associated periodic syndrome (CAPS) defines a group of autoinflammatory diseases, characterized by recurrent episodes of systemic inflammatory attacks in the absence of infection or autoimmune disease. "However, in most IL-1–related autoinflammatory conditions, such as cryopyrin-associated periodic syndromes (CAPS), no mutations exist in the IL1RN or IL1B genes." (PMID 40668918, 2025).